IL6 (interleukin 6)
Diseases named in the same sentence as IL6 in open-access papers (continued):
Sharing a sentence is not in itself a finding about the gene and the disease.
vitiligo (67 papers, 2005 to 2026). Generalized well circumscribed patches of leukoderma that are generally distributed over symmetric body locations and is due to autoimmune destruction of melanocytes. "Several cytokines implicated in vitiligo pathogenesis—including IL-17, IL-2, IL-6, IL-8, TNF-α, and IFN-γ—are regulated, at least in part, by vitamin D and its analogs." (PMID 41157208, 2025). "ELISAs showed that inflammatory cytokines associated with vitiligo, such as IFNγ, IL6, and CXCL10 were significantly elevated in CUMS serum." (PMID 40361040, 2025). "The clinical association between vitiligo and OP is similarly attributed to the shared influence of pro-inflammatory cytokines, such as IL-17, IL-6, and IL-2, which affect bone remodeling." (PMID 39796035, 2024). "We aimed also to find a possible interplay between ACE gene polymorphism with the inflammatory mediator IL-6 and/or cellular cytotoxicity induced by serum nitrite in vitiligo patients." (PMID 26177100, 2015). "In conclusion, this study discovers that plasma IFN-γ, IFN-γ-regulated chemokines, including CXCL9, CXCL10 and CXCL11, and IL-6 might be potential biomarkers for vitiligo recurrence, with CXCL9 also associated with disease activity." (PMID 39981245, 2025). "Plasma IFN-γ, CXCL9, CXCL10, CXCL11 and IL-6 might be potential biomarkers for vitiligo recurrence, with CXCL9 also associated with disease activity." (PMID 39981245, 2025). "The elevated production of IL-6 in vitiligo has been associated with melanocytic cytotoxicity." (PMID 37998534, 2023). "The pathogenesis of these might be linked to cytokines which also play a role in vitiligo pathogenesis, such as IL-1, IL-6, TNF-α, and possibly IL-17." (PMID 34445526, 2021). "Serum IL-6 and serum nitrite play a role in the pathogenesis of vitiligo and the D allele of the ACE I/D gene polymorphism may confer susceptibility to vitiligo." (PMID 26177100, 2015). "Our second aim was to find a possible association between ACE gene polymorphism and inflammatory mediators (as interleukin (IL)-6) and/or cellular cytotoxicity induced by serum nitrite (as a breakdown product of the cytotoxic nitric oxide) in vitiligo patients." (PMID 26177100, 2015). "Moreover, imiquimod can induce cytokines such as IFN-α, TNF-α, IL-6, IL-8, and nitric oxide to cause vitiligo." (PMID 24928346, 2014). "Correlation analysis showed a positive relationship between IFN-γ, CXCL9, CXCL10, CXCL11, IL-6, and IL-15 in the plasma of patients with recurrent vitiligo." (PMID 39981245, 2025). "Then, ROC curve analysis for IFN-γ, CXCL9, CXCL10, CXCL11 and IL-6 in recurrent versus persistent stable vitiligo were conducted." (PMID 39981245, 2025). "The elevated levels of proinflammatory cytokines, particularly TNF-α and IL-6, in the current study patients support previous reports linking these mediators to vitiligo pathogenesis and activity." (PMID 40723924, 2025). "To further investigate the anti-inflammatory ability of FHB on vitiligo mice at the transcriptional level, we used PCR to detect the expression of IL-6 and TNF-α in the lesioned skin." (PMID 37575231, 2023). "Another study reported a significant decrease in serum IL-6 in vitiligo patients receiving ginkgo biloba for 4 weeks compared to placebo." (PMID 38136202, 2023). "Cytokines (e.g., TNF-α and IL-6) -mediated inflammation is important in the development of vitiligo, and CHE and TYR are molecules related to melanin synthesis." (PMID 37575231, 2023). "In comparison to the control group, HQ-induced vitiligo mice had a significant increase of IL-6 and TNF-α in both skin tissues and melanocytes, but FHB therapy can effectively decrease them." (PMID 37575231, 2023). "The FHB therapy group significantly reduced the levels of inflammatory factors TNF-α and IL-6 in the blood of vitiligo mice, which was consistent with the results anticipated by network pharmacology." (PMID 37575231, 2023).
vitiligo (continued). "Higher IFN-γ and IL-6 levels have been observed in the blood and skin of vitiligo patients and are indexes for vitiligo diagnosis." (PMID 33959187, 2021). "Increased serum levels of IL-6 are reported in patients with vitiligo, in particular in those with new lesions." (PMID 34768860, 2021). "Accordingly, we also detected a significant induction of IL-6 expression in both vitiligo cell populations after being treated with 3-MA." (PMID 33767135, 2021). "Cytokines have remarkable roles in the pathogenesis of vitiligo, such as IL-1, IL-6, and TNF-α; interleukin 27 (IL-27) is a new member of the IL-6/IL-12 family, mainly released by activated antigen-presenting cells." (PMID 32616337, 2020). "In the current study serum IL-6 was significantly higher in vitiligo patients when compared to healthy subjects." (PMID 26177100, 2015). "Both IL-6, as a proinflammatory cytokine, and NO, as a cytotoxic agent, have been suggested to play a role in the pathogenesis of vitiligo." (PMID 26177100, 2015). "Serum levels of ACE, IL-6 and nitrite in vitiligo patients were statistically significantly higher than those in controls." (PMID 26177100, 2015). "High level of IL-6 in the lesional skin of vitiligo was indicated to be relevant to the failure of melanocyte transplantation therapy (unpublished data)." (PMID 24681574, 2014). "Taken together, our findings support the idea that IFN-γ directly decreases the viability of melanocytes, and meanwhile it helps create a vitiligo-prone milieu by enhancing the release of some autoimmune accelerators such as IL-6 and HSP-70." (PMID 24681574, 2014). "IL-6 levels are significantly elevated in the blood and the local microenvironment of vitiligo patients." (PMID 23042234, 2013). "Our results showed that, except for IL-15, the levels of these factors were significantly higher in recurrent patients compared to persistent stable patients, which suggest that increased levels of IFN-γ, CXCL9, CXCL10, CXCL11 and IL-6 are potential triggers for vitiligo recurrence." (PMID 39981245, 2025). "Based on previous research, we propose a hypothesis that IFN-γ, CXCL9, CXCL10, CXCL11, IL-6, and IL-15 are involved in the recurrence of vitiligo and are interconnected." (PMID 39981245, 2025). "Additionally, IFN-γ, CXCL9, CXCL11, and IL-6 also exhibit substantial individual predictive capabilities for vitiligo recurrence, with AUC values of 0.806, 0.773, 0.785, and 0.709, respectively." (PMID 39981245, 2025). "The upregulation of IL-6 is also reported in vitiligo patients." (PMID 39981245, 2025). "Based on the existed research on the pathogenesis of vitiligo, it was hypothesized in present study that IFN-γ, IFN-γ-regulated chemokines, IL-6 and IL-15 are associated with disease activity and also predictive biomarkers for disease recurrence in vitiligo." (PMID 39981245, 2025). "Tocilizumab therapy has been found to increase serum IL-6 levels following IL-6R blockage; this increase could potentially have systemic effects, such as exacerbating vitiligo by intensifying the imbalance between Tregs and Th17 cells." (PMID 39201060, 2024). "Alternatively, reduced intake of confection might generate hypoglycemia, which stimulates the generation of mitochondrial ROS29 or cellular heat shock–related responses and increases blood IL‐6 levels, triggering vitiligo." (PMID 38421796, 2024). "Moreover, as the level of IL-6 in sera positively correlates with disease progression, it can be regarded as a sensitive marker of active vitiligo." (PMID 39201060, 2024). "Indeed, patients with vitiligo have been found to demonstrate higher IL-6 serum concentrations than controls." (PMID 39201060, 2024).
vitiligo (continued). "Serum IL-1β and serum IL-6 (vitiligo > AA) are also elevated in both diseases, supporting the hypothesis that oxidative stress is associated with the promotion and amplification of inflammatory process in both AA and vitiligo." (PMID 38673994, 2024). "To assess whether LBP influences innate immune responses in the skin of mice with monobenzone-induced vitiligo, we measured IL-8, IL-6, TNF-α, IFN-γ and IL-1β expression by RT-qPCR." (PMID 36655287, 2023). "Activation of XBP-1 was involved in 4-TBP-induced IL-6 expression that might contribute to the autoimmune-mediated progression of vitiligo." (PMID 37627575, 2023). "Increased levels of IL-6 are reported in patients diagnosed with vitiligo." (PMID 37998534, 2023). "Enhanced expression of LOC100506314 inhibited the phosphorylation of STAT3, protein kinase B (AKT), and extracellular signal-regulated protein kinases (ERK), as well as the levels of nuclear protein of p65 and the expression of IL-6 and IL-17 in Jurkat cells and T cells from patients with vitiligo." (PMID 37731844, 2023). "Finally, the transfection of LOC100506314 effectively suppressed the expression of IL-6 and IL-17 in T cells from patients with vitiligo, which are known to be elevated in the serum of patients with vitiligo." (PMID 37731844, 2023). "IL-6 is a vital immune factor involved in autoimmune inflammation in vitiligo." (PMID 36569347, 2022). "In fact, this herbal derivate may induce reduction in TNF-α and IL-6, both of which are increased in vitiligo patients and known inhibitors of human melanocyte proliferation and melanogenesis." (PMID 34356320, 2021). "Moreover, a specific IL-6 polymorphism, IL6-572 G/C, has been proposed to be associated with vitiligo susceptibility in the Gujarat population." (PMID 34768860, 2021). "Moreover, p16 was also up-modulated as protein and a transient enhanced release of IL-6 was even observed at the protein level by ELISA assay on culture supernatants of vitiligo melanocytes, particularly after 48 h of treatment with 3-MA." (PMID 33767135, 2021). "Interestingly, keratinocytes in vitiligo lesions aberrantly produce IL-1, IL-6, and TNF-α, which inhibit melanocyte function and elicit an inflammatory response." (PMID 33717132, 2021). "Interestingly, some studies point to the connection between the higher level of IL-6 in the tissue and/or serum and the presence of autoimmune disorders accompanying vitiligo." (PMID 32443482, 2020). "An increase in the production of IL-6 in vitiligo has a reported role in melanocytic cytotoxicity." (PMID 26177100, 2015). "Also the current study revealed a significant positive correlation between serum IL-6 and nitrite in vitiligo patients, suggesting a possible relation between these factors in the pathogenesis of vitiligo." (PMID 26177100, 2015). "Increasing serum and/or lesional skin levels of IL-6 have been documented in vitiligo." (PMID 24681574, 2014). "Moreover, increased levels of soluble interleukin (IL)-2 receptor, IL-6, and IL-8 have been found, which further suggest the role of T-cell activation in the vitiligo pathogenesis." (PMID 22778983, 2012). "An increased level of soluble interleukin (IL)-2 receptor, IL-6 and IL-8 has been observed in vitiligo patients, which further suggests that T cell activation may be a component in vitiligo pathogenesis." (PMID 16303054, 2005). "Furthermore, the rise in these pro-inflammatory cytokines, such as tumour necrosis factor (TNF), interleukin 1 (IL-1), interleukin 6, and other inflammatory factors engaged in vitiligo, are known to be involved in stimulating insulin resistance and atherosclerosis." (PMID 39337683, 2024). "Increased IL-6 expression may contribute to the autoimmune-mediated progression of vitiligo." (PMID 37627575, 2023). "Increased IL-6 levels may contribute to vitiligo’s autoimmune-mediated progression." (PMID 37627575, 2023). "Furthermore, higher expression of IL‐6 and IL‐8 have been found in vitiligo lesions." (PMID 34614305, 2022).
vitiligo (continued). "In vitiligo, IL-33 may be considered an alarmin; it may be released by apoptotic or necrotic keratinocytes and inhibits melanocytes growth, blocking growth factors and increasing pro-inflammatory IL-6 and TNFα expression." (PMID 34768860, 2021). "Therefore, IL-6 might have a role in the activation of immune responses following oxidative injuries in vitiligo." (PMID 34768860, 2021). "Serum IL-6 and nitrite levels might have an important role in the pathogenesis of vitiligo." (PMID 26177100, 2015). "Moreover, vitiligo melanocytes produced many biologically active proteins among the senescence-associated secretory phenotype (SAPS), such as interleukin-6 (IL-6), matrix metallo proteinase-3 (MMP3), cyclooxygenase-2 (Cox-2), insulin-like growth factor-binding protein-3 and 7 (IGFBP3, IGFBP7)." (PMID 23555779, 2013). "Patients with vitiligo presented higher circulating levels of IFN-λ1 and IL-1b and ratios of IFN-λ1/IL-10 and IL-6/IL-10 (p < 0.05, p < 0.05, p < 0.001, and p < 0.01, respectively)." (PMID 42052095, 2026). "This study further demonstrates the significant upregulation of miRNA-146a and proinflammatory mediators (NF-κB, IL-6, and TNF-α), accompanied by the downregulation of Foxp3 in vitiligo tissues." (PMID 40723924, 2025). "These aldehydes also activate immune responses by functioning as DAMPs, stimulating dendritic cells and inducing pro-inflammatory cytokines such as IL-6, IL-1β, and TNF-α, contributing to vitiligo’s autoimmune component." (PMID 40427437, 2025). "Several inflammatory and immune‐related pathways showed significant upregulation in vitiligo, including IL1, IL6, TNF, MHC‐I, MHC‐II, and various cytokine signaling cascades." (PMID 41498037, 2025). "The measurements revealed significantly higher levels of both IL-6 and CXCL10 in vitiligo patients compared to controls." (PMID 39337683, 2024). "The findings showed that patients with active vitiligo had increased levels of ROS, high levels of MDA, AND IL‐6, TNF‐a, IL‐1b, IFN, and IL‐8." (PMID 39313936, 2024). "It has also been demonstrated that IL-6 and CXCL10 are reliable markers of vitiligo activity status." (PMID 39337683, 2024). "The serum of monobenzone-induced vitiligo mice exhibited a marked increase in proinflammatory cytokines, such as TNF-α, IFN-γ, and IL-6." (PMID 38542385, 2024). "IL-1β, HMGB1, IL-8, and IL-6 TNF-α are believed to have a crucial role in the innate immune response, and their levels were considerably increased in vitiligo patients' serum and skin." (PMID 36920542, 2023). "In the present study, we observed increased levels of IL-8, IL-6, TNF-α, IFN-γ and IL-1β in the skin of monobenzone-induced vitiligo mice, and LBP significantly inhibited secretion of IL-8, IL-6, TNF-α, IFN-γ and IL-1β." (PMID 36655287, 2023). "In this study, we employed 4-TBP, a known inducer of vitiligo, to trigger ER stress and activate the UPR in human melanocytes, leading to an increase in cytokine IL-6 expression." (PMID 37627575, 2023). "In the skin and serum of patients with vitiligo, UPR promotes the production of the chemokines IL-6 and IL-8 through the transcription factor X-box-binding protein 1 (XBP1)." (PMID 35884944, 2022). "In patients with vitiligo, PBMCs can secrete proinflammatory cytokines such as IL-1β, IL-6, IL-8, and tumor necrosis factor (TNF)-a, and infiltrate around the lesions of vitiligo, suggesting that PBMCs play important roles in the pathogenesis of vitiligo." (PMID 34941177, 2021). "This is associated with higher melanocyte apoptosis and production of pro-inflammatory cytokines IL-6 and TNF-α in vitiligo." (PMID 33717132, 2021). "To check for the possible signs of systemic inflammation, we measured the concentration of inflammation-associated cytokines (TNF-α, IFN-γ, IL-1b, IL-1Ra, IL-2, IL-5, IL-6, CXCL8, CXCL10, G-CSF, and GM-CSF) in the plasma of vitiligo patients." (PMID 30515176, 2018).
vitiligo (continued). "In this study, vitiligo patients showed a significant higher VIDA score, higher serum IL-6 and higher nitrite in patients with the DD genotype of ACE polymorphism." (PMID 26177100, 2015). "Interfering with Mfsd4a in melanocytes co-cultured with vitiligo model T cells significantly improved melanocyte activity, inhibited the levels of inflammatory cytokines TNF-α, IL-1β, and IL-6, reduced melanocyte apoptosis, and inhibited JAK/STAT3 pathway activation." (PMID 40707941, 2025). "IFN-γ, CXCL9, CXCL10, CXCL11, IL-6, and IL-15 were expressed at higher levels in the circulation of patients with both segmental and non-segmental vitiligo compared to healthy controls (p < 0.001)." (PMID 39981245, 2025). "The IHC-positive areas of IL-6 and TNF-α of the FHB high-dose treatment group (HQ+7.2g/kg FHB) were even lower than those of the control group, indicating that FHB strongly inhibited inflammation in the topical vitiligo skin." (PMID 37575231, 2023). "In addition, increased levels of innate immunity cytokines including interleukin (IL)-1α, IL-1β, IL-6, IL-8, IL-12, IL-15 and tumor necrosis factor (TNF)-α have been detected in the sera of patients with vitiligo." (PMID 35884944, 2022). "Interleukin (IL)-1β, IL-6, and tumor necrosis factor alpha (TNF-α) are inflammatory cytokines, which are anti-melanogenic factors and are upregulated in the skin and sera in patients with vitiligo." (PMID 34638746, 2021). "Interestingly, they also observed significantly decreased levels of IL-6, TNF-α, IFN-γ, and IL-13 in sera of vitiligo mice models." (PMID 33613564, 2020). "This confirms the previous observations that IL-6 and IL-8 levels are elevated in the sera of vitiligo patients while the TNF-α and IFN-γ levels are decreased, and that IL-6 is highly produced in the vitiligo lesional skin." (PMID 23042234, 2013). "In vitiligo affected skin, a significantly higher expression of TNFA, IL6, and IFNG was detected compared with healthy controls and perilesional, non-lesional skin indicating that cytokine imbalance plays an important role in the depigmentation process of vitiligo." (PMID 24312346, 2013). "Furthermore, detection of significantly higher expression of IL-6 and tumor necrosis factor (TNF)-α in vitiligo skin, compared with normal skin, reveals an imbalance of epidermal cytokines at sites of lesions." (PMID 22778983, 2012). "EGCG significantly attenuated histopathologic changes (vitiligo) in the skin by reducing excessive inflammatory responses, especially the infiltration of CD8+ T cells, and by markedly inhibiting inflammatory mediators such as tumor necrosis factor‐alpha (TNF‐α) and IL‐6 levels." (PMID 41243839, 2025). "The potential mechanism of imiquimod-induced vitiligo involves interaction with Toll-like receptor 7 (TLR7) present on skin cells, which stimulates the production of various cytokines, including interferon (IFN)-α, tumor necrosis factor alpha (TNF-α), interleukin (IL)-6, IL-1, IL-8, and IL-12." (PMID 40920788, 2025). "Interestingly, IL-6 showed a strong positive correlation with the other five factors, which suggest that the interaction between IL-6 and IFN-γ in the induction of IFN-γ-regulated genes may also play a role in the pathogenesis of vitiligo recurrence." (PMID 39981245, 2025). "Pro-inflammatory cytokines such as tumor necrosis factor alpha (TNF-α), interleukin-6 (IL-6), interleukin-8 (IL-8), interleukin-1β (IL-1β), IFN-γ, and some anti-inflammatory cytokines such as interleukin-5 (IL-5) and IL-10 are increased in patients with active vitiligo." (PMID 36439174, 2022). "Another hypothesis is that HLA-G expressed on the skin of vitiligo patients interacts with KIR2DL4 receptors from NK cells, and this interaction may induce the production of proinflammatory cytokines such as IFN-γ, TNF-α, IL-1α, IL-1β, IL-6, and IL-8." (PMID 31505868, 2019).